MIR637 (microRNA 637)
Synonyms: hsa-mir-637; MIRN637
Gene: MicroRNA gene on chromosome 19 (3,961,414 to 3,961,512, reverse strand). Ensembl gene ENSG00000283928.
Diseases named in the same sentence as MIR637 in open-access papers:
MIR637 is named in the same sentence as 2 diseases in open-access papers, as found by Europe PMC text mining. Sharing a sentence is not in itself a finding about the gene and the disease. The quoted sentences say what the papers report.
clear cell renal cell carcinoma (1 paper, 2024). "MIR637 is down-regulated in most cancers and up-regulated in clear cell renal cell carcinoma." (PMID 39020437, 2024).
MIR637 also shares sentences with these, for which no sentence is quoted: cancer (1 paper).